EGFR (epidermal growth factor receptor)
Diseases named in the same sentence as EGFR in open-access papers (continued):
Sharing a sentence is not in itself a finding about the gene and the disease.
lung cancer (continued). "Hyperthermia promotes accumulation of intracellular cisplatin in EGFR mutation positive lung cancer cells." (PMID 26654941, 2016). "On the other hand, clinical outcomes in subgroups of lung cancer patients have been improved by identifying and targeting key oncogenic driver mutations, such as activating EGFR mutations." (PMID 26716514, 2016). "Increased expression of HER2 was observed in exon 21 L858R and exon 19 E746-A750 deletion mutation EGFR genes transfected A549 lung cancer stable cells." (PMID 27362942, 2016). "Herein, we evaluated both the EGFR mutation frequency and spectrum in familial lung cancer patients." (PMID 27449093, 2016). "In this paper, we have focused on the prediction of ligands’ conformations to the EGFR, whose structure can be altered by mutations in lung cancer patients." (PMID 27869781, 2016). "Obtaining an adequate amount of tissue at the time of lung cancer diagnosis is essential for accurately diagnosing the histologic differentiation and molecular status of the tumor, which includes identifying EGFR mutations." (PMID 27685950, 2016). "EGFR mutation in lung cancer was often found to result in the activation of signal transducers and activators of transcription 3 (STAT3)." (PMID 27486770, 2016). "Further RT-PCR analysis also showed an increased expression of CDH5 mRNA in lung cancer cells with EGFR mutations." (PMID 27362942, 2016). "For example, the EGFR test specifically interrogates potential exon 19 deletions and L858R mutations, which constitute about 85% of EGFR mutations in lung cancers." (PMID 27043212, 2016). "Our unpublished data also showed that overexpression of mutant EGFR genes were associated with upregulation of VEGF in lung cancer cells." (PMID 27362942, 2016). "Our data also demonstrated that EGFR mutated or KRAS mutated lung cancers are associated with higher nuclear YAP1 expression in comparison to EGFR/KRAS wild type tumors." (PMID 26716514, 2016). "In the present study, we also evaluated the association between YAP1 germline mutation and EGFR mutation status among lung cancer families (Cohort-2)." (PMID 27449093, 2016). "We have shown that activating EGFR mutations are correlated with increased CK 19 expression in human lung cancers." (PMID 26979333, 2016). "Several cancers, including glioblastoma multiforme, lung cancer and anal cancers, are associated with overexpression of epidermal growth factor receptor (EGFR)." (PMID 27875990, 2016). "A significant portion of lung cancer patients harbor kinase domain mutations in the epidermal growth factor receptor (EGFR)." (PMID 26654941, 2016). "In summary, our study shows that exon 19 deletion mutant EGFR gene is associated with an increased expression of CDH5 in lung cancer cells through increased phosphorylation of EGFR and Akt pathways." (PMID 27362942, 2016). "These EGFR mutated lung cancer cells (such as PC9) are sensitive to the EGFR-TKIs including gefitinib." (PMID 27690301, 2016). "The twin brothers in our study were diagnosed with advanced stage lung cancer at the same age and they shared the same histology and EGFR mutation subtype." (PMID 27449093, 2016). "As in other reported cases of chordoma, our patient’s tumor lacks the EGFR mutations that are associated with response to EGFR inhibition in lung cancer." (PMID 27200287, 2016). "We used PC9 cells, a lung cancer cell line carrying EGFR mutation, because this is a validated target for EGFR tyrosine kinase inhibitors (TKI)." (PMID 27270313, 2016). "In this study, we show that depletion of SALL4 by shRNA resulted in a decreased in cell viability and tumorigenicity of SALL4-positive lung cancer cells, which were associated with dysregulation of both EGFR and IGF1R signaling pathways." (PMID 27705911, 2016). "We used a lung cancer cell line carrying a mutation in the epidermal growth factor receptor gene (EGFR) because this is a validated target for EGFR tyrosine kinase inhibitors (EGFR-TKIs)." (PMID 27270313, 2016).
lung cancer (continued). "Of these many different mechanisms of resistance, approximately half of all lung carcinomas with acquired resistance to EGFR TKIs develop a T790M point mutation in exon 20 of EGFR." (PMID 27533086, 2016). "Activating mutations of the EGFR gene are found in a subset of lung carcinomas (10% of adenocarcinomas in the Caucasian population) and define a subpopulation of cancers that can benefit from oral EGFR tyrosine kinase inhibitors (TKIs)." (PMID 27027238, 2016). "In many published studies, a wide range in the prevalence of EGFR mutations has been reported in lung carcinomas, from 7.5 % in Norway, 8.8 % in a mixed ethnic population in the USA, to 10 to 15 % in Europe, to more than 50 % in Asian countries." (PMID 27655296, 2016). "Globally considered, these results suggest that the heterogeneity of a driver-gene mutation, such as that of EGFR in lung cancer is a rare molecular event." (PMID 25904052, 2015). "The dysregulation and/or hyperactivation of the EGFR signaling pathway are frequently found in epithelial lung tumor entities, in which the hyperactivated EGFR signaling is associated with advanced lung cancer and poor prognosis." (PMID 26273639, 2015). "Efforts have been made to identify driver oncogene mutation after the development of epidermal growth factor receptor (EGFR) tyrosine kinase inhibitors targeting EGFR in lung cancer." (PMID 25742289, 2015). "Due to more powerful drugs and the introduction of a targeted therapy for molecularly selected patient subgroups like patients with an EGFR activation mutation, impressive improvements in the treatment of lung cancer patients were achieved." (PMID 25675432, 2015). "Together, these mutations account for approximately 85% of the EGFR mutations observed in lung cancer; tumors with these mutations are highly sensitive to treatment with erlotinib, gefitinib, and the second-generation EGFR inhibitor afatinib." (PMID 26134262, 2015). "Preclinical data showed that introducing activated PIK3CA mutations into EGFR-mutated lung cancer cell lines confers resistance to EGFR-TKIs." (PMID 26175928, 2015). "The characterization of EGFR activating mutations which predict sensitivity or resistance to anti-EGFR therapies has provided a basis for selecting lung cancer patients for targeted therapies." (PMID 26208325, 2015). "To conclude, in this study we report the frequency of EGFR mutations in a cohort of 956 lung cancer patients as well as the frequency of alterations in KRAS, BRAF, MET, PIK3CA and ALK genes in a subset of these patients." (PMID 26208325, 2015). "Our results contrast the findings made in lung cancer patients where the EGFR T790M mutation is a typical „second mutation”observed under therapeutic pressure during ongoing TKI-therapy." (PMID 26267891, 2015). "Activating mutations in the EGFR gene, such as a deletion on exon 19 and a point mutation in exon 21, identifies a distinct subset of lung cancers that are uniquely sensitive to EGFR-TKIs." (PMID 26354324, 2015). "We found that expression of EGFR-L858R in lung cancer cells resulted in up-regulation of the CXCR4 in association with increased cancer cell invasive ability and MPE formation." (PMID 26338423, 2015). "This review not only introduces the biology and clinical implementations of ctDNA but also includes the updating information of recent advancement of techniques for detecting EGFR mutation using ctDNA in lung cancer." (PMID 26448936, 2015). "We evaluated 35 lung cancer samples with EGFR mutation from adenocarcinoma patients who had received gefitinib." (PMID 25886066, 2015). "Targeted inhibition of EGFR with a small molecule kinase inhibitor has been successful for lung cancer with EGFR mutations." (PMID 25928246, 2015). "Patients suffering from lung cancers that harbor EGFR-sensitive mutations are responsive to reversible EGFR tyrosine kinase inhibitors (TKIs) such as erlotinib." (PMID 25760241, 2015).
lung cancer (continued). "EGFR inhibitors including erlotinib are used clinically to treat lung cancers carrying activating EGFR mutations, but are less effective against lung cancers with wildtype EGFR." (PMID 26556242, 2015). "As a proof of principle, CRE is able to detect the activating EGFR L858R and T790M EGFR mutations in lung cancer cell line and primary tumors." (PMID 27127615, 2015). "The finding that EGFR mutations in primary lung cancer are associated with sensitivity to EGFR inhibitors gefitinib and erlotinib contributed greatly to the final approval of these therapeutics for the treatment of lung cancer." (PMID 26134262, 2015). "In the current study, we reported that CXCR4 surface protein expression in clinical samples from lung cancer patients with tumors expressing the EGFR-L858R mutation is significantly higher than that in tumors expressing EGFR-WT." (PMID 26338423, 2015). "Epidermal growth factor receptor (EGFR) is the best-known target gene for lung cancer, which mutates in a relatively high frequency of 20–30% and tyrosine kinase inhibitors (TKIs) are particularly effective for treating these patients." (PMID 25905642, 2015). "In lung cancers, ER expression was reported to correlate with female sex, less smoking history, smaller tumor size, adenocarcinoma histology, and EGFR mutation." (PMID 26318038, 2015). "A similar explanation also underlies the mutual exclusivity for KRAS and EGFR mutations seen in lung cancer." (PMID 26427375, 2015). "In the present study, IL-8 is highly associated with the cellular stemness and EGFR TKI resistance in lung cancer cells." (PMID 25871388, 2015). "Mass spectrometry has been applied in detection of EGFR mutations in plasma DNA from lung cancer patients." (PMID 26448936, 2015). "The clinical success of gefitinib, an inhibitor of EGFR, in a subset of lung cancers with mutations in the TK domain of EGFR, holds a promise for the future of targeted therapy 33, 34, and also leads to the investigation of analogous mutations of HER‐2." (PMID 26305917, 2015). "Exploring the clinicopathological characteristics of lung cancer with EGFR mutations is considered very important for lung cancer treatment." (PMID 26496308, 2015). "Despite a limited statistical data, high expression group of miR-34c also showed poor overall survival than low expression one, especially in EGFR exon 19 mutation lung cancer patients." (PMID 26170125, 2015). "EGFR tyrosine kinase inhibitors (TKIs) as single agents have shown potent clinical benefits in lung cancer patients harboring EGFR-activating mutations." (PMID 26568478, 2015). "Lung cancer in Asians is also genetically diverse with up to 35 % of patients harboring epidermal growth factor receptor (EGFR) mutations in contrast to only 10 % of Caucasian patients." (PMID 26582178, 2015). "This study was designed to investigate epidermal growth factor receptor (EGFR) mutation types affecting lung cancer treatment in patients in Xinjiang, China." (PMID 25886900, 2015). "Recently, in lung cancers the positive association between ER expression and EGFR mutations has been detected, and the potential clinical impact of ERα, ERβ, and PR has also been investigated." (PMID 26318038, 2015). "In the landmark Iressa Pan-ASia Study (IPASS) study, gefitinib (Iressa), a mutated epidermal growth factor receptor (EGFR) inhibitor, demonstrated superiority to carboplatin and paclitaxel in treating patients with lung cancer in East Asia." (PMID 26220301, 2015). "With the use of these methods, we characterized and estimated the frequency of somatic EGFR mutations in a set of lung cancer samples from central Poland." (PMID 25719557, 2015).
lung cancer (continued). "For example, compared with lung cancer patients of European ancestry, Asian patients carry more EGFR mutations and exhibit higher clinical response rates to EGFR tyrosine kinase inhibitors." (PMID 26870154, 2015). "Our data provide mechanistic insights into the activation of 10 different C-terminal deletion variants including GBM and lung cancer-derived EGFR mutants." (PMID 25826094, 2015). "We also evaluated IC50 values for afatinib in gefitinib-resistant human lung cancer H1975 cells carrying de novo T790M mutation, and in H460 cells which express wild-type of EGFR but carrying KRAS mutation which leads to gefitinib resistance." (PMID 25714021, 2015). "For instance, Twist1 expression is associated with EGFR mutation in lung adenocarcinoma from non-smokers, and a cooperative effect between EGF pathway activation and Twist1 reactivation promotes EMT in EGFR mutated lung cancer." (PMID 26360779, 2015). "The identification of oncogenic driver mutations in lung cancer has led to the rapid rise of genotype-directed target therapy such as EGFR tyrosine kinase inhibitors (TKIs) and has shown dramatic clinical benefits." (PMID 26448936, 2015). "The common EGFR-activating mutations, exon 19 deletions and L858R, which account for 85% of all EGFR mutations, predict sensitivity to the EGFR TKIs (gefitinib, erlotinib and afatinib) in preclinical models and in patients with lung cancer." (PMID 25978031, 2015). "In general, lung cancers caused by activating EGFR mutations are initially responsive to TKIs until second mutations, such as T790M, emerge and confer resistance by sterically blocking binding of TKIs." (PMID 25760241, 2015). "Targeting ‘driver’ mutations including EGFR in lung cancer and BRAF in melanoma resulted in great clinical success." (PMID 26544513, 2015). "The ongoing phase 1 study of avitinib in China in lung cancer patients with T790M mutation will provide the first set of clinical data of third-generation EGFR inhibitors in Chinese patients." (PMID 26220301, 2015). "Surface expression of CXCR4 protein on lung cancer cells harboring the EGFR-L858R mutation (median, 12.61; range: 8.95–34.56) was significantly higher than that in EGFR-WT cells (median, 5.36; range, 2.00–12.58; P = 0.025, Mann-Whitney U Test)." (PMID 26338423, 2015). "The study showed how inhibition of NF-κB signaling enhances erlotinib-induced apoptosis in lung cancer cells harboring activating mutations of EGFR." (PMID 26015408, 2015). "Our findings contrast with the observations made in lung cancer patients where the EGFR-T790M-mutation is classified as a typical „second mutation”causing resistance to TKI-therapy during ongoing anticancer therapy." (PMID 26267891, 2015). "Adenocarcinoma is the most common histological subtype of lung cancer, and somatic mutation of the epidermal growth factor receptor (EGFR) is present in approximately 40% and 20% of these tumors in East-Asians and Caucasians, respectively." (PMID 25875914, 2015). "EGFR inhibitors such as gefitinib and erlotinib are used in lung cancer therapy where EGFR overexpression is implicated." (PMID 26057128, 2015). "Further evaluation is necessary to examine the factors that conclusively differentiate unresectable advanced lung cancer from resectable lung cancer in patients harboring the same EGFR mutation." (PMID 26496308, 2015). "Meanwhile, mutations that result in EGFR overexpression or over-activity have also been implicated in a number of cancers, including lung cancer, in particular non-small cell lung cancer." (PMID 25730907, 2015). "Recent studies in lung adenocarcinoma of female nonsmokers also revealed that the expression of miR-183-3p, miR-195, and miR-122 was in plasma and associated with EGFR mutations in lung cancer." (PMID 26273639, 2015). "Abnormally elevated EGFR signaling is associated with many common human solid tumors, including lung cancer." (PMID 26439803, 2015).
lung cancer (continued). "This indicates that selective combinatorial treatment should be used for cells with wild type EGFR and T790M mutated EGFR, to improve lung cancer patient prognosis." (PMID 26301867, 2015). "Nonetheless, the effectiveness of dasatinib is poor in both lung cancer A549 cells with wild-type EGFR or in H1975 cells harbouring L858R and T790M mutations, which is similar to the medical outcome of gefitinib treatment." (PMID 26312766, 2015). "Consistently, EGFR activation is associated with tumor radioresistance and poor prognosis in GBMs and lung cancers." (PMID 26546517, 2015). "The EGFR pathway plays an important role in lung cancer, especially EGFR mutations which have opened up the possibility of a personalized medicine approach to this disease." (PMID 25810955, 2015). "Lung cancers with epidermal growth factor receptor (EGFR) gene mutation account for ~40% of lung adenocarcinomas in East Asians and ~20% in Caucasians and African Americans1." (PMID 26400668, 2015). "EGFR-mutations have been studied in lung cancer for some years and are established as important markers in guiding therapy with tyrosine kinase inhibitors (TKIs)." (PMID 26267891, 2015). "Breast cancer cells were shown to upregulate ErbB3 via multiple mechanisms to escape pharmacological EGFR inhibition, and in lung cancer cells, autocrine activation of ErbB3 caused resistance to the EGFR-specific small molecule inhibitor Gefitinib." (PMID 25630670, 2015). "ddPCR can quantify mutations in the EGFR gene in lung cancer at the single-molecule level, making it possible to detect samples with low mutation rates." (PMID 25780439, 2015). "Nevertheless, the identification of EGFR mutations in patients with lung cancer remains of great importance for their clinical management and prognosis." (PMID 25683726, 2015). "EGFR inhibitor therapy is now the standard of care in the treatment of advanced lung cancers with EGFR mutations." (PMID 26697520, 2015). "Assessment of the epidermal growth factor receptor (EGFR) mutational status has become crucial in recent years in the molecular classification of patients with lung cancer." (PMID 25683726, 2015). "We validated the expression of three miRNAs in ninety lung cancers, consisting of thirty-eight EGFR exon 19 mutation patients, forty EGFR exon 21 mutation ones, twelve wild type ones, and eleven normal control lung tissue, by qRT-PCR." (PMID 26170125, 2015). "Today, we have multiple EGFR-TKI options to treat patients with lung cancer harboring EGFR mutations." (PMID 26515464, 2015). "Taken together, our results provided direct evidence that activation of IGF1R is one of the mechanisms underlying acquired drug resistance to EGFR-TKIs in lung cancer cells." (PMID 26554308, 2015). "Recently, several studies have demonstrated that EGFR is a target of a number of miRNAs, and vice versa a mutation or activity of the EGFR signaling pathway can alter the expressions of miRNAs in lung cancer." (PMID 26273639, 2015). "We also found that lung cancer cells harboring the EGFR-L858R mutation promoted the formation of MPE in vivo." (PMID 26338423, 2015). "Mutations that lead to EGFR overexpression or hyperactivity have been associated with a number of cancers, including lung cancer." (PMID 26513174, 2015). "The epidermal growth factor receptor (EGFR) gene and its pathways was the first oncogenic driver discovered to be mutated and treatable in lung cancer." (PMID 25810955, 2015). "Lung cancer patients with EGFR mutation (ie, exon 19 deletions or exon 21 L858R point mutations) achieve a substantially increased benefit from treatment with EGFR tyrosine kinase inhibitor, compared with standard chemotherapy." (PMID 26170125, 2015). "Methods used in selected previous reports to detect EGFR gene mutations in plasma and serum samples of lung cancer patients." (PMID 26047516, 2015).